CRP (C-reactive protein)
Diseases named in the same sentence as CRP in open-access papers (continued):
Sharing a sentence is not in itself a finding about the gene and the disease.
infection (continued). "Other factors associated with complications were, WBC ≥ 12,000/μL, CRP ≥ 10 mg/L, a positive microbiological test, infection sustained by S. aureus and a positive MRI." (PMID 28471400, 2017). "When GABHS is cultured from the oropharynx and is associated with an antibody response suggesting a true infection, CRP will elevate 80–90% of the time." (PMID 28991170, 2017). "The present study assesses the accuracy of the individual or grouped diagnostic tests for PJI, including CRP, histopathology and microbiology tests, based on the time of infection after prosthesis implantation." (PMID 28841913, 2017). "Infections were associated with splenic volume, leukocyte counts, percentage of Treg cells, and serum levels of CRP, IL-10, and IFN-?" (PMID 27682880, 2017). "First, our results differentiated between those infections that were associated with higher CRP and those associated with lower CRP." (PMID 28571565, 2017). "The delayed onset of infection, changes in bacterial strains during treatment, and elevated CRP levels at discharge do increase the risk for treatment failure." (PMID 28592300, 2017). "Infections were associated with splenic volume, leukocyte counts, the percentage of Treg cells, and serum levels of CRP, IL-10, and IFN-γ." (PMID 27682880, 2017). "Clinically, the CRP detection is usually used to differentiate the infection caused by bacteria from virus." (PMID 29203814, 2017). "Being an inflammatory factor produced by the liver that increases in response to infection or inflammation, CRP has been associated with chronic disease and sedentary lifestyle." (PMID 29059178, 2017). "Among the many infections detected, several were associated with higher CRP and/or a higher likelihood of an elevated CRP." (PMID 28571565, 2017). "The early postoperative infections resulted in an increase of CRP, ESR, and PCT greater than that associated with trauma and surgery which occurs in the first 2 weeks after surgery." (PMID 29138696, 2017). "Caution is required when interpreting CRP concentrations in pregnant and lactating women who have co-existing nutrient deficiencies and multiple infections." (PMID 28571565, 2017). "This highlights the complexity of the associations of pathogens and CRP, and raises questions about how to interpret CRP in settings with multiple infections." (PMID 28571565, 2017). "Individuals with P. vivax mono-infections had the highest plasma CRP concentrations with the greatest association with parasitaemia." (PMID 27386859, 2016). "In a multivariable log-scale linear regression model adjusting for host characteristics and M.tb strain type, infection with the East African Indian strain was associated with significantly lower baseline-CRP (fold-change in CRP 0.51 (0.34–0.77), p < 0.01)." (PMID 27287260, 2016). "All children with serious infection had one of the at-risk features sought by the clinical decision rule and thus all received CRP testing." (PMID 27716201, 2016). "In primary care, CRP testing can be restricted to children at higher risk of serious infection after clinical assessment." (PMID 27716201, 2016). "In this setting persistent malaria infections in asymptomatic individuals were associated with moderately elevated plasma CRP concentrations; chiefly evident in cases with P. vivax mono-infections." (PMID 27386859, 2016). "In particular, elevation and distance to the nearest health facility were consistently associated with infection when it was defined using parasitaemia, either alone or in combination with CRP or fever." (PMID 27391972, 2016). "In Model 1, age (6–23 months), and baseline iron status were positively associated with infection (CRP > 5 mg/L and/or parasitaemia), while length-for-age z-score, and weight-for-length z-score were negatively associated with infection status." (PMID 27391972, 2016).
infection (continued). "Nonetheless, CRP is primarily produced in the liver and its specificity as diagnostic and prognostic tool for infection is limited in cirrhotic patients with compromised liver function, which will underestimate the severity of acute infection." (PMID 27861595, 2016). "Blood samples with elevated infection markers (CRP > 5 mg/L and/or AGP > 1 g/L) were associated with a higher mean ferritin but lower mean retinol, α-/β-carotene and tryptophan." (PMID 26821044, 2016). "For infection defined using CRP only, there appeared to be well-defined high- and low-risk areas that tended to cluster around villages." (PMID 27391972, 2016). "In the multivariate analysis, female gender and high baseline CRP were predictable risk factors for the infection in hospitalized cirrhotic patients." (PMID 26498833, 2015). "Illnesses that usually cause obvious changes in CRP levels include infection, burns, trauma, inflammatory disease, and malignancy." (PMID 26247033, 2015). "Patients with SA were associated with lower rates of pulmonary exacerbations and CRP than those with “PA”, suggesting that infection with SA is a marker of less severe disease." (PMID 26093634, 2015). "Demographic data, APACHE II scores, diagnoses on admission, clinical pulmonary infection scores (CPIS), CRP, procalcitonin, risk factors for infection, time to VAP diagnosis, and bacteriological culture results were recorded." (PMID 26870112, 2015). "For these reasons, the postoperative kinetics of systemic CRP concentrations need further investigation to differentiate between elevation related to a surgical procedure and elevation associated with infection in the postoperative course." (PMID 25585544, 2015). "Of note, the multivariate analysis revealed an independent association of IL-10 and CRP with infections, suggesting a strong effect of the inflammatory and anti-inflammatory reaction on the development of infections." (PMID 25613713, 2015). "As CRP is a non-specific marker of inflammation, the precise cause of high CRP (infection, wound healing, diet, stress, or some other factor) cannot be ascertained." (PMID 26675298, 2015). "The sensitivity of CRP is known to be the lowest during the early stages of infection, while its diagnostic accuracy improves by the performance of serial CRP determinations and by its combination with earlier markers such as interleukins or procalcitonin." (PMID 25685774, 2015). "Acute injuries, such as trauma, infection or surgery, cause the release of interleukin-6 and other cytokines that trigger the synthesis of CRP by the liver." (PMID 25159658, 2015). "Univariate Cox regression analysis revealed that ΔMPV72h-adm, male sex, APACHE II and SOFA score, RRT, platelet count, CRP level, lactate level, and infection site were significantly associated with an increased risk of 28-day all-cause mortality." (PMID 25742300, 2015). "Among children aged >5 years, higher CRP was also significantly associated with higher ferritin concentrations, which can be regarded as a marker of cellular responses to infection and injury." (PMID 24603645, 2014). "PCT is generally considered a more reliable marker than CRP in defining infection as a cause of SIRS, although other authors concluded that both biomarkers have similar diagnostic accuracy." (PMID 24903083, 2014). "CRP is a widely studied marker of inflammation and infection and it is also used in heart disease risk assessment, progression and treatment effectiveness." (PMID 24481229, 2014). "Routine laboratory data including the ESR and CRP are noted to have a high diagnostic accuracy towards infection." (PMID 25257938, 2014). "In that study, the combination of CRP > 87 mg/L and body temperature > 38.2°C was associated with infection diagnosis with a specificity of 100%." (PMID 23547830, 2013).
infection (continued). "C-reactive protein is an acute phase protein that reflects the systemic inflammatory response to infection and has prognostic value in patients with HIV-associated TB in this cohort." (PMID 24168211, 2013). "It is sometimes difficult to distinguish an infection from an exacerbation of the disease in patients with immune-inflammatory disorders associated with elevated serum CRP concentrations." (PMID 23207551, 2013). "Patients presenting maximum daily CRP variation > 4.1 mg/dL and a CRP level > 87 mg/L had an 88% risk of infection." (PMID 23547830, 2013). "Determinations of C-reactive protein levels have been shown to be useful in the diagnostic evaluation of neonates with suspected infection." (PMID 23365583, 2013). "Our data is in agreement with a recent study which focused on deep infections, where CRP-286 (C>T>A) polymorphism is found to be significantly associated with maximal CRP levels during the first week of infection." (PMID 23941472, 2013). "CRP, a well-known marker of infection, was also shown to associate with the hostility trait in humans." (PMID 23922720, 2013). "This study however, suggests that CRP changes are more associated with evolution of infection and PCT more with evolution of adverse infectious sequelae." (PMID 23762396, 2013). "Patients with this cut-off of 8.7 mg/dL associated with a daily variation in CRP >4.1 mg/dL had an 88% risk of infection." (PMID 24286072, 2013). "A CRP concentration >10 mg/dL was associated with proven infection in 73% of the patients as compared to 31% when the CRP was <1 mg/dL." (PMID 24286072, 2013). "This study demonstrates a novel method for electrical detection of C-reactive protein (CRP) as a means of identifying an infection in the body, or as a cardiovascular disease risk assay." (PMID 23899933, 2013). "From the ROC curves, ADN ratio was a better predictor of postoperative infection compared with blood loss, operating time, or CRP levels." (PMID 23520452, 2013). "The current EB for CRP testing in pediatric infections is weak and suggests that CRP is of low diagnostic value." (PMID 22943554, 2012). "Better quality research is needed to definitively determine the diagnostic accuracy of CRP levels in children with infections." (PMID 22943554, 2012). "Of particular interest is the association among serum IL-22, CRP and spontaneous bacterial peritonitis, indicating that IL-22 production is augmented by the infection." (PMID 22967278, 2012). "The major transcriptional patterns identified included a pro-inflammatory myeloid signature, linked to sampling early in the course of infection, high neutrophil and monocyte counts, and elevated CRP (C1)." (PMID 22496797, 2012). "The P. acnes infection caused an increase in serum CRP throughout the studied period, with a peak value of 627 μg/ml 3 weeks post infection." (PMID 23240022, 2012). "Dosing schemes of MMPI vary widely from 40 mg daily and upwards, including the usual adult antibiotic dose of 100 mg twice daily used in this proof of concept study, a dose reported to reduce CRP levels during inflammation associated with infection." (PMID 23025537, 2012). "CRP is a component of the “acute phase response” associated with infection, inflammation, and tissue damage." (PMID 22645408, 2012). "The evidence in support of the diagnostic utility of CRP levels for pediatric infections is weak and is mostly based on studies of low levels of evidence." (PMID 22943554, 2012). "It should be noted, however, that all previous studies varied in their choice of the optimal CRP cutoff value, which adds to the controversy regarding the diagnostic benefit of the CRP level for pediatric infections." (PMID 22943554, 2012). "CRP on the other hand, is thought to be a general marker of systemic inflammation, of which infection is one common cause." (PMID 21366899, 2011).
infection (continued). "For CRP, the American Heart Association has suggested that the serum CRP values of >10 mg/L imply the presence of active infection or inflammation but that values between 3 and 10 mg/L are indicative of an increased risk of CVDs." (PMID 22106757, 2011). "Serum CRP levels dramatically increase in case of any infection or tissue damage caused by trauma and it is therefore controversial to start aggressive treatment solely based on elevated CRP levels." (PMID 22294971, 2011). "Elevated levels of LBP, IL-6 and CRP were associated with a more severe level of infection in children." (PMID 20158885, 2010). "Inflammation and tissue injury are the classical broad initiation signals for CRP release through the IL-6 mechanism, however, more specifically, infection is a typical cause for CRP elevation." (PMID 19948067, 2009). "Acute phase proteins such as CRP and cytokines are elevated markedly in association with infection and inflammation." (PMID 19180241, 2009). "Procalcitonin (PCT) and C-reactive protein (CRP) measurements have been shown to improve the clinical accuracy in identifying patients with SIRS caused by infection from SIRS of other causes." (PMID 18426596, 2008). "On the second postoperative day, CRP greater than 30 mg/l (OR = 8.27; 95% CI: 1.05-64.79; p = 0.03) in association with infection and IL-6 higher than 50 pg/ml was marginally significant (OR = 8.31; 95% CI: 0.81-84.50; p = 0.07)." (PMID 17505683, 2007). "Because PCT concentration changes more rapidly than CRP in response to infection (bacterial and/or fungal), a diagnostic decision can be taken more precociously, which would aid in speeding up choosing the therapeutic conduct." (PMID 18034890, 2007). "Numerous studies have evaluated the usefulness of different markers, such as CRP and procalcitonin, both in the diagnosis of and in the identification of patients at risk of infection." (PMID 16635270, 2006). "Our study data suggest that LBP (cut off level 20 μg/ml), CRP (cut off level 30 mg/l) and IL-6 (cut off level 16.3 pg/ml) are comparable in terms of their diagnostic abilities in diagnosing infection." (PMID 16569262, 2006). "Patients presenting maximum daily CRP variation >4.1 mg/dl plus a CRP level >8.7 mg/dl had an 88% risk of infection." (PMID 16635270, 2006). "Probiotics significantly reduced postoperative infections (risk ratio = 0.49, 95% CI: 0.26-0.92, p = 0.027) and C-reactive protein elevation (risk ratio = 0.42, 95% CI: 0.26-0.68, p < 0.001) and increased Bifidobacterium abundance (standardized mean difference = 0.84, 95% CI: 0.51-1.17, p < 0.001)." (PMID 42073379, 2026). "Severity-of-illness indices (SAPS-II and MCCI) and inflammation-based biomarkers (NLR, PLR, CRP, and IL-6) were closely linked to both the timing of infection onset and in-hospital mortality, highlighting their potential value for early risk stratification in critically ill patients." (PMID 41597404, 2026). "IL-6, IL-4, and CRP may work as risk indicators of developing joint pain and chronic arthritis after the infection’s acute phase." (PMID 41598488, 2026). "Albumin, with its antioxidant and anti-inflammatory properties, is neuroprotective, while CRP is a commonly used inflammatory marker in clinical practice to reflect the degree of inflammation at the onset of infection and is associated with the severity, infarct size, and prognosis of AIS patients." (PMID 40697568, 2025). "IL-6 has long been recognized for its involvement in acute phase response to infection, inflammation, or tissue damage through stimulation of hepatocytes to secrete acute-phase proteins such as C-reactive protein (CRP), a diagnostic marker of inflammation and microbial infection." (PMID 39857830, 2025). "Thus far, most investigations have quantified plasma C-reactive protein (CRP) to explore how graded inflammatory responses affect surgical results and infection risk." (PMID 41446750, 2025).
infection (continued). "The elevated CRP levels in patients with B. pseudomallei (mean CRP: 197.23 mg/L) approached significance (p = 0.06), also supporting previous reports of stronger inflammatory markers in infections caused by this species." (PMID 39897275, 2025). "Patient age (>54 years old) and elevated CRP levels (>5 times the reference value) help to decide whether to prescribe antibiotics, in the case of suspected infection associated with acute renal colic (Grade of recommendation: C; Level of evidence: 4)." (PMID 40080792, 2025). "Furthermore, PCT testing conducted within 48 h post-surgery has been demonstrated to be an effective predictor of postoperative infection, exhibiting diagnostic accuracy that is considered to be superior to that of C-reactive protein (CRP)." (PMID 40336598, 2025). "While CRP monitoring can inform antibiotic stewardship, its association with prescribing decisions is probably only modest, underscoring the need to integrate a range of clinical factors to optimise infection management." (PMID 40764898, 2025). "A decrease in CRP after grafting may serve as a useful prognostic indicator, whereas an unexpected increase could signal a heightened risk of infection." (PMID 40507966, 2025). "CRP levels have been shown to correlate with cancer burden and disease progression, although their diagnostic interpretation requires caution, as levels are often affected by comorbidities and infection status." (PMID 40362613, 2025). "Changes in CRP levels (the difference between admission and previous CRP levels) had a better diagnostic value compared to the admission CRP level alone in predicting infection that would prevent chemotherapy in patients with SCLC and in patients with comorbidities." (PMID 40125102, 2025). "C-reactive protein (CRP), an acute-phase reactive protein, has a diagnostic value in infections." (PMID 40276743, 2025). "Elevated CRP, IL-6, and procalcitonin levels may signal the need for enhanced postoperative monitoring and infection risk management." (PMID 39857688, 2025). "Available diagnostic tests that assist this process include microbiologic culture and polymerase chain reaction (PCR) for pathogen identification, hematologic indices and biomarkers associated with infection or inflammation such as C-reactive protein (CRP) and procalcitonin." (PMID 40901476, 2025). "This study highlights that accessible biomarkers such as CRP and procalcitonin may support the early identification of pediatric oncology patients at risk of severe infection." (PMID 40688982, 2025). "The clinical presentation of mycotic aneurysms includes fever, neurological symptoms, immunosuppression, vascular risk factors, and evidence of infection, including elevated C-reactive protein (CRP), erythrocyte sedimentation rate (ESR), leukocytosis, and positive blood cultures." (PMID 41399559, 2025). "Also, CRP KO mice were more susceptible than WT mice to infection, although the difference between the MST curves for female WT and female KO mice was not statistically significant." (PMID 40740789, 2025). "Using CRP as a marker to identify patients suitable for these therapies may inadvertently select those at higher risk of infection-related complications." (PMID 40796058, 2025). "The minimal change in other effects, combined with the overall slight model performance improvement (AUROC from 0.84 to 0.86), indicates that while CRP refines risk prediction for certain subgroups, particularly in the context of suspected infections, the core mortality predictors remain unchanged." (PMID 40764898, 2025). "Given the timing of peak concentrations of IL-6 relative to CRP, there might be an advantage in infection risk prediction for IL-6 when assessing infection risk directly postoperative." (PMID 40549692, 2025). "In this context, CRP is used as a screening tool for an ongoing infection which might increase the risk of early bacterial colonization of the newly implanted endoprosthesis." (PMID 40001448, 2025).